TCF21 (transcription factor 21)
Diseases named in the same sentence as TCF21 in open-access papers (continued):
Sharing a sentence is not in itself a finding about the gene and the disease.
breast carcinoma (10 papers, 2016 to 2021). "Resembling the tumors described to date, TCF21 is less expressed in human breast cancer cell lines and tissues and is associated with larger tumor mass size and lymphoid metastases." (PMID 33729392, 2021). "The associations of TCF21 rs12190287 polymorphism with breast cancer risk were further examined with stratification by age, pathological type and tumor stage." (PMID 27270650, 2016). "Logistic regression analyses showed that TCF21 rs12190287 polymorphism was significantly associated with the reduced risk of breast cancer." (PMID 27270650, 2016). "Analysis of the genetic polymorphism of TCF21 and the risk of breast cancer in Chinese women suggests that the TCF21 rs12190287 polymorphism can regulate TCF21 expression and may serve as a potential marker for genetic susceptibility to breast cancer." (PMID 33729392, 2021). "Taken together, our findings suggest that TCF21 rs12190287 polymorphism can regulate TCF21 expression and may serve as a potential marker for genetic susceptibility to breast cancer in Chinese women." (PMID 27270650, 2016). "The purpose of this study is to investigate whether TCF21 genetic polymorphisms(rs2327429 T>C, rs2327430 T>C, rs2327433 A>G, rs12190287 C>G, rs7766238 G>A, rs4896011 T>A) are associated with the risk of breast cancer in Chinese women." (PMID 27270650, 2016). "To test this hypothesis, we conducted a hospital-based case-control study to evaluate the influence of TCF21 SNPs on the risk of breast cancer in Chinese women." (PMID 27270650, 2016). "Therefore, we hypothesized that SNPs in TCF21 gene might be associated with breast cancer risk by altering TCF21 expression." (PMID 27270650, 2016). "Overexpression of TCF21 in MDA-MB-231 breast cancer cells decreased cell proliferation, invasion, and migration capacity and inhibited angiogenesis, epithelial-mesenchymal transition, and apoptosis." (PMID 33729392, 2021). "The TCF21 mechanism of action in human breast tumor cell lines showed that TCF21 is able to regulate aberrant estrogen receptor-α signaling (Erα), an important factor for the progression of breast cancer, thereby reducing its functionality." (PMID 33729392, 2021). "The tumor suppressor function of TCF21 is also demonstrated in different tumors such as lung, colorectal and breast cancer, where the activation of TCF21 expression reduced cell growth, EMT and suppress migration and invasion." (PMID 35201460, 2021). "TCF21 has also been reported as a tumor suppressor gene in gastric cancer, colorectal cancer, head and neck carcinomas, and breast cancer." (PMID 31430859, 2019). "Some specific targets and pathways were mainly enriched in the c2.all.v6.2.entrez.gmt gene set, suggesting that progression of MPM may partly be involved in the invasive pathways of breast cancer and pathways related to TCF21 and SMARCA2 targets." (PMID 33968720, 2021). "Both PBRM1 and TCF21 have been shown to have tumor suppressor-like functions in breast cancer." (PMID 31430859, 2019). "Since sumoylation of TCF21 could repress the transcriptional activity of ERα, and down-regulate its target genes expression, we speculated that sumoylation of TCF21 may also inhibit the proliferation of ERα-positive breast cancer cells." (PMID 27028856, 2016). "In addition, crystal violet staining assay was conducted to further confirm the inhibition of TCF21 on the proliferation of ERα-positive breast cancer cells." (PMID 27028856, 2016). "Taken together, these results suggested that TCF21 could repress the growth of breast cancer cells, and this process was dependent on TCF21 sumoylation." (PMID 27028856, 2016). "Moreover, overexpression of either wild-type or mutant TCF21(K24R) could inhibit the growth of breast cancer cells, but mutant TCF21 showed weaker ability to repress the growth of breast cancer cells than wild-type TCF21." (PMID 27028856, 2016).
breast carcinoma (continued). "In this study, we showed that in human ERα-positive breast cancer cell lines, TCF21 participated in the ERα-signaling pathway through acting as a negative regulator of ERα, and the interaction between TCF21 and ERα could inhibit the transcriptional activity of ERα." (PMID 27028856, 2016). "In addition, TCF21 expression was downregulated in most breast cancer tissues, and TCF21 overexpression could inhibit the proliferation of human breast cancer cell line MDA-MB-231." (PMID 27270650, 2016). "However, little is known about the role of TCF21 in human breast cancer." (PMID 27028856, 2016). "Therefore, elucidating the relationship between TCF21 and ERα network will further uncover the molecular mechanism of TCF21 in regulating cell functions, and this may provide better insight for conceiving a way to combat breast cancer." (PMID 27028856, 2016). "In order to investigate this possibility, immunoprecipitation (IP) experiment was conducted in two different ERα-positive breast cancer cell lines, MCF-7 and T47D, using either anti-TCF21 or anti-ERα antibody." (PMID 27028856, 2016).
colorectal cancer (10 papers, 2011 to 2026). A primary or metastatic malignant neoplasm that affects the colon or rectum. "For instance, the upregulation of TCF21 inhibits the metastasis of esophageal squamous cell carcinoma and colorectal cancer." (PMID 38084139, 2023). "Furthermore, our results that overexpression of TCF21 inhibits migration are in accordance with in vitro studies in colorectal cancer cell lines as well as siRNA suppression of endogenous TCF21 in renal progenitor cells which increased migration." (PMID 29080283, 2018). "TCF21 was aberrantly methylated and silenced in head and neck squamous cell carcinoma and non-small-cell lung cancer; C2orf40 was hypermethylated and transcriptional silenced in colorectal carcinoma and glioma, and its over-expression led to a significant decrease in cell growth." (PMID 21799901, 2011). "More recently, TCF21 was found to induce KISS-1 and reduce MMPs expression through the PI3K/Akt pathway in colorectal cancer." (PMID 35201460, 2021).
gastric cancer (8 papers, 2016 to 2024). A primary or metastatic malignant neoplasm involving the stomach. "In colorectal and gastric cancer cells, downregulation of TCF21 by hypermethylation induces cell proliferation, migration, and invasion, probably through inactivation of PI3K/AKT signaling." (PMID 33729392, 2021). "Both the genetic variants rs12190287 of TCF21 and rs10046 of CYP19A1 have been studied in multiple cancers which include breast, lung, neck, and gastric cancer." (PMID 32487238, 2020). "It was found that TCF21 in gastric carcinoma cells was highly methylated than in the normal adjacent cells." (PMID 32487238, 2020). "However, the association of TCF21 genetic polymorphisms with gastric cancer (GC) susceptibility and prognosis remains unclear." (PMID 38714991, 2024).
head and neck squamous cell carcinoma (7 papers, 2011 to 2021). A squamous cell carcinoma that arises from any of the following anatomic sites: lip and oral cavity, nasal cavity, paranasal sinuses, pharynx, larynx, and salivary glands. "TCF21 is expressed in normal lung airway epithelial cells, however, it is aberrantly methylated and silenced in the majority of head and neck squamous cell carcinomas and in NSCLC." (PMID 29169318, 2017). "This colocalization is responsible for demethylation of the TCF21 promoter, and its subsequent activation mediates hydroxy-methylation of CpG residues through association with the TET protein family, a key intermediate step important in head and neck squamous cell carcinoma (HNSCC)." (PMID 31658672, 2019). "TARID and TCF21 are silent and heavily covered by DNA methylation in non-small cell lung cancer (NSCLC), head and neck squamous cell carcinomas (HNSCC) and ovarian cancers (OVC)." (PMID 28747406, 2017).
non-small cell lung carcinoma (7 papers, 2011 to 2023). A group of at least three distinct histological types of lung cancer, including non-small cell squamous cell carcinoma, adenocarcinoma, and large cell carcinoma. "TCF21 is silenced in squamous cell carcinomas, non-small-cell lung cancer cells, and clear cell renal cell carcinoma." (PMID 28476165, 2017).
bladder cancer (6 papers, 2021 to 2023). "The TCF21 gene (6q23.2) is active in the embryonal mesoderm surrounding the genitourinary system and is also involved in bladder cancer." (PMID 36349425, 2023). "One interesting duplication finding on chromosome 6 (6q23.2) contains the 3′ end of the gene Transcription Factor 21 (TCF21), that is active in the embryological mesoderm surrounding the genitourinary system and a prognostic marker in bladder cancer." (PMID 36349425, 2023). "A study showed that TCF21 inhibited lymph node metastasis in bladder cancer (Mokkapati, Porten & Narayan, 2020)." (PMID 37123010, 2023). "miR-3648 is overexpressed and promotes invasion and metastasis of human bladder cancer by directing transcription factor 21 (TCF21)/kisspeptin 1 (KISS1) axis." (PMID 35037826, 2022). "PCDH17 and TCF21 promoter methylation levels provided a sensitivity rate of 96% for prostate cancer, 92% for bladder cancer, and 67% for renal cell tumors." (PMID 33729392, 2021). "A previous study of miRNA-3648 reported that upregulation of this miRNA led to inhibition of TCF21, and thereby promoted the invasion and metastasis of bladder cancer." (PMID 33816220, 2021). "Additionally, the increase in miR-3648 regulates the TCF21/KISS1 association, resulting in the promotion of invasion and metastasis of human bladder cancer." (PMID 33729392, 2021). "Similar to miR-21 activity in ccRCC, in human invasive bladder cancer cells, UMUC3 and T24T cell lines, miR-3648 inhibits TCF21 protein expression by reducing its mRNA stability." (PMID 33729392, 2021).
head and neck cancer (6 papers, 2011 to 2019). A primary or metastatic malignant neoplasm affecting the head and neck. "TCF21 is a transcription factor demonstrated in lung and head and neck cancers to be inactivated by epigenetic mechanisms." (PMID 24194935, 2013). "TCF21 is considered to be a candidate tumour suppressor at 6q23-q24 that is epigenetically inactivated in lung, head and neck cancers." (PMID 22369099, 2011).
Hypertension (6 papers, 2017 to 2024). The presence of chronic increased pressure in the systemic arterial system. "In the present study, we showed that T2DM, hypertension, and hyperlipidemia status were significantly associated with genotypes of TCF21 are consistent with previous studies 22,24." (PMID 38250610, 2024). "Rs2954029 (TRIB1) is associated with sleep regulation and increased expression during sleep deprivation, which in turn is closely correlated with stress whereas rs12190287 (TCF21) is a possible susceptibility locus for hypertension." (PMID 28426714, 2017). "A significant correlation was found between the polymorphism of TCF21 rs76987554 and hypertension." (PMID 32582717, 2020). "Therefore, we inferred that TCF21 might contribute to the genetic susceptibility to CHD by affecting the predisposition to hypertension." (PMID 32582717, 2020). "All of the QTLs showed enrichment for blood pressure and hypertension phenotypes which are highly consistent with known SMC functions, and association of TCF21 with blood pressure has been identified by population studies with multiple racial ethnic groups." (PMID 32513244, 2020).
liver fibrosis (6 papers, 2022 to 2025). "The authors also reported that DNMT3a is responsible for the low expression of TCF21 in liver fibrosis." (PMID 39201329, 2024). "Recently, the transcription factors GATA-binding factor 6 (GATA6) and transcription factor 21 (Tcf21) were identified as factors inhibiting profibrotic HSCs, thereby promoting liver fibrosis regression." (PMID 35805998, 2022). "Furthermore, the expression of peroxisome proliferator-activated receptor (PPAR)γ, GATA-binding factor 6 (GATA6), GATA4, and transcription factor 21 (TCF21) appears to play a role in regulating HSC reversion to an inactive state in liver fibrosis 42-44." (PMID 39897543, 2025). "TCF21 has been identified as a deactivation factor for HSCs in murine models of hepatic fibrosis, thereby providing a potential therapeutic target for the otherwise intractable liver fibrosis." (PMID 39201329, 2024). "Recent study identified TCF21 as a deactivation factor of fibrogenic HSCs in liver fibrosis." (PMID 36875100, 2023). "In addition, overexpression of transcription factor 21 (Tcf21) suppresses activation and partially restores the quiescent phenotype of active HSCs, accompanied by regression of liver fibrosis." (PMID 35933403, 2022).
metastatic melanoma (6 papers, 2015 to 2021). A melanoma that has spread from its primary site to another anatomic site. "Since then, TCF21 promoter hypermethylation has been associated with poor outcome in various tumor types, including metastatic melanoma, lung adenocarcinomas, squamous cell lung cancers, clear cell renal cell carcinoma and other urological cancers." (PMID 26158413, 2015). "In addition, downregulation of TCF21 through hypermethylation has been reported to be associated with poor outcome in patients with ccRCC and metastatic melanoma." (PMID 29080283, 2018). "Moreover, TCF21 promoter DNA methylation is correlated with decreased survival in metastatic melanoma." (PMID 33729392, 2021). "TCF21 is recognized as a candidate tumor suppressor and has been reported to be epigenetically inactivated due to aberrant methylation of the TCF21 gene promoter in a wide range of malignancies, including metastatic melanoma, head and neck, lung, gastric and urological cancers." (PMID 27028856, 2016).
adrenocortical tumor (5 papers, 2015 to 2021). "Despite few defined markers for adrenocortical tumors (ACTs), TCF21 is less expressed in ACC than in adenomas (ACA) and normal tissue." (PMID 33729392, 2021). "We further investigate the potential molecular mechanism regulated by TCF21 in adrenocortical tumor cells." (PMID 35201460, 2021). "In this study, it was investigated the correlation between TCF21 expression and the promoter methylation status in adrenocortical tumor cells, carcinomas and adenoma." (PMID 35201460, 2021). "Taken together, these data indicate that adrenocortical tumor cells become less likely to migrate upon presence of TCF21 expression." (PMID 35201460, 2021). "In the present study, it was investigated the correlation between TCF21 expression and the promoter methylation status in adrenocortical tumor cells, carcinoma and adenoma cells, and the biological function and potential molecular mechanism of TCF21 in motility of ACC cells." (PMID 35201460, 2021). "Analysis of TCF21 expression in different adrenocortical tumor cell cultures showed lower mRNA expression of TCF21 in human ACC cells; H295R cells and ACC-T36 cells when compared to cell culture from pediatric adenoma, ACAPed-T7 and human normal adrenal pool (NA), which was used as reference." (PMID 35201460, 2021). "Taken together, these findings support the hypothesis that Transcription Factor 21 is a regulator of steroidogenic factor 1 and is a tumor suppressor gene in pediatric and adult adrenocortical tumors." (PMID 28658440, 2017). "The aim of this study was to investigate whether silencing or overexpression of the gene Transcription Factor 21 could modulate the gene and protein expression of steroidogenic factor 1 in adrenocortical tumors." (PMID 28658440, 2017). "POD-1/TCF21 may play a crucial role in adrenal and gonadal homeostasis and represses Sf-1/SF-1 expression in adrenocortical tumor cells." (PMID 26421305, 2015). "One of common mechanism in many human tumors is the hypermethylation-mediated silenced expression of TCF21, which has not yet been studied in adrenocortical tumors." (PMID 35201460, 2021). "More recently, analysis of the combined expression of TCF21 and BUB1B in adult and pediatric adrenocortical tumors showed a negative correlation between the expression levels of TCF21 and BUB1B in adult ACCs." (PMID 33729392, 2021). "Thus, it could be reported that TCF21 is downregulated in ACC and regulates the steroidogenic factor 1 (SF-1) and StAR protein (steroidogenic acute regulatory protein) binding to the SF-1 E-box promoter in adrenocortical tumor and normal adrenal cells." (PMID 35201460, 2021).
clear cell renal cell carcinoma (5 papers, 2015 to 2021). "A literature search revealed that TCF21 hypermethylation is also present in clear cell renal cell carcinomas (ccRCC): renal tumors with another biology and phenotype, which most often occur in adults." (PMID 29080283, 2018). "As there are no in vitro models of CCSK, we employed a well‐established clear cell renal cell carcinoma (ccRCC) cell line, 786‐O, which also manifests high methylation at the TCF21 promoter, with consequent low TCF21 expression." (PMID 29080283, 2018).
endometriosis (5 papers, 2020 to 2025). The growth of functional endometrial tissue in anatomic sites outside the uterine body. "Furthermore, TCF21 has recently been shown to drive fibrosis associated with ovarian and deep infiltrating endometriosis." (PMID 32984350, 2020). "One study evaluated how IL-4 and IL-13 increase the expression of periostin and TCF21, which are involved in the regulation of fibrosis in endometriosis." (PMID 38337827, 2024). "While it is unknown if this estrogen activation is widespread throughout the body, it is interesting to note that TCF21 also regulates fibrosis in endometriosis." (PMID 40182431, 2025). "Suppressing FOXP1 reverted the endometrium cell phenotype, involving decreased collagen gel contraction, cell growth and migratory movement.TCF21 could transactivate SF-1 and Erβ promoters in ESCs, modulating estrogen pathway and fibrosis of endometriosis." (PMID 38844959, 2024). "TCF21 may be a promising therapeutic target and biomarker in endometriosis." (PMID 38337827, 2024). "TCF21 interacts with USF2 in endometriotic stromal cells and activates the promoters of SF-1 and estrogen receptor beta, thereby influencing the estrogen pathway in endometriosis." (PMID 40182431, 2025). "Periostin and transcription factor 21 TCF21 is not detected in the stromal cells of women without endometriosis, but it is strongly detected in deep endometriosis." (PMID 38337827, 2024).